GSTO1 (glutathione S-transferase omega 1)
Diseases named in the same sentence as GSTO1 in open-access papers (continued):
Sharing a sentence is not in itself a finding about the gene and the disease.
cancer (30 papers, 2007 to 2025). A tumor composed of atypical neoplastic, often pleomorphic cells that invade other tissues. "Cisplatin‐induced GSTO1‐associated EVs showed anti‐cancer activities by dramatically impairing tumor colony formation and migration abilities." (PMID 38750006, 2024). "Several polymorphisms in the GST omega class have been acknowledged as cancer-risk biomarkers, but, to the best of our knowledge, this is the first study investigating the association of GSTO1 polymorphic expression in relation to testicular tumorigenesis." (PMID 37374052, 2023). "GSTO1 overexpression and polymorphism has been associated with several pathological diseases including neurological disorders, cancers, and inflammatory diseases." (PMID 37894945, 2023). "Recently, signaling events involving interaction of GSTO1 with type 1 ryanodine receptor, RyR1 has been implicated in a signaling pathway that stimulates cancer stem cell enrichment during chemotherapy." (PMID 30487385, 2018). "Glutathione S-transferase omega 1 (GSTO1) is an atypical GST isoform that is overexpressed in several cancers and has been implicated in drug resistance." (PMID 27703239, 2016). "We further observed that the lead GSTO1 inhibitor C1-27 blocked cancer cell proliferation, caused cytotoxicity, inhibited cell cycle progression and increased the sensitivity of cancer cells to cisplatin." (PMID 27703239, 2016). "Glutathione S-transferase omega 1 (GSTO1) is an atypical GST isoform overexpressed in several cancers that has been implicated in drug resistance." (PMID 27703239, 2016). "This suggests that the control of cisplatin levels in cells could be the key to GSTO1‐associated cisplatin resistance in cancer cells." (PMID 38750006, 2024). "GSTO1, a gene of the glutathione S-transferase family, is upregulated in a variety of highly aggressive cancer cells." (PMID 40108736, 2025). "In particular, GstO1 is highly expressed in cancer cells and is involved in regulating signaling pathways for cancer development." (PMID 38791319, 2024). "Glutathione S-transferase omega 1 (GSTO1) has been shown to be overexpressed in a variety of cancer cells." (PMID 36497451, 2022). "Recent studies have demonstrated two SNPs in GSTO gene [GSTO1 (rs4925: C>A) and GSTO2 (rs156697: A>G)] being associated with different cancer types, and majority of these studies have substantiated GSTO2 as a risk factor for various solid tumors." (PMID 34722260, 2021). "Recently, novel aspect of GSTO1-1 role in cancer progression is shown to be mediated by interaction with type 1 ryanodine receptor, RyR1." (PMID 31861116, 2019). "The researchers reported that the loss of either glutathione S-transferase omega 1 (GSTO1) or RYR1, reduced the number of cancer stem cells in the primary tumor." (PMID 29443735, 2018). "To determine the significance of such overexpression, we evaluated the effect of silencing GSTO1 on cancer cell viability." (PMID 27703239, 2016). "Here we show that silencing of GSTO1 with siRNA significantly impairs cancer cell viability, validating GSTO1 as a potential new target in oncology." (PMID 27703239, 2016). "We have identified a family of chloroacetamide-containing compounds with potent inhibitory activity against GSTO1 and efficacy against cancer cells in both in vitro and in vivo models." (PMID 27703239, 2016). "GSTO1 inhibitors show efficacy against cancer cells in both in vitro and in vivo models and enhance the cytotoxic effects of cisplatin." (PMID 27703239, 2016).
cancer (continued). "In peripheral blood lymphocytes, the levels of GSTO1 expression and localization remain stable until cancer formation, which presumably represents a stimulus for induction and nuclear relocation of the enzyme." (PMID 26046795, 2015). "Analysis of GSTO1/O2 showed that among the CAE ≥ 20 subjects, the diplotype AGG/AGG had a significantly increased cancer risk compared to CAA/CAA subjects with an estimated HR of 4.91 (95% CI, 1.02-23.74, p = 0.05)." (PMID 21798077, 2011). "In addition, GSTO1 is suggested to be involved in chemoresistance in ovarian, colon, and cervical cancers." (PMID 38750006, 2024). "The role of GSTO1 in cancer progression has attracted increasing attention over the past few years." (PMID 38750006, 2024). "In addition, anti-apoptotic and pro-survival role of GSTO1 was acknowledged as an important part of cellular chemoresistance strategy in some cancer cell lines." (PMID 37374052, 2023). "ECA has been found to inhibit GSTO1 activity, a protein that is involved in cancer cell migration." (PMID 37047688, 2023). "Many GSTs, e.g., GSTO1, GSTP1, GSTK1, GSTA4 and GSTM3, are reported to cause resistance in cancer." (PMID 36428646, 2022). "Considering influence of those targeted therapies on redox state, research concerning GSTO1 inhibitors in cancers could be valuable." (PMID 31861116, 2019). "Additionally, they demonstrated that GSTO1-1 knockdown blocks cancer stem cell enrichment, tumor initiation and metastasis." (PMID 31861116, 2019). "We show here in a panel of cancer cell lines that GSTO1 knockdown reduced cancer cell viability." (PMID 27703239, 2016). "Treatment with GSTO1-specific siRNA significantly decreased the viability of HCT116 cancer cells." (PMID 27703239, 2016). "Interestingly, the pro-survival function of GSTO1 in cancer cells appeared to be cancer- or cell type-specific." (PMID 27703239, 2016). "Taken together, our findings validate GSTO1 as an important drug target for cancer therapeutics." (PMID 27703239, 2016). "Moreover, our potent inhibitors serve as valuable tools to investigate the role of GSTO1 in cancer and other pathologies, as well as to uncover additional functions in the cell." (PMID 27703239, 2016). "Similarly, we observed an upregulation of GSTO1 mRNA in different cancer cell lines (HCT116, MDA-MB-435 and MDA-MB-231) by analysing transcript data in BioGPS." (PMID 27703239, 2016). "We further show using siRNA that GSTO1 is an important survival factor for cancer cells." (PMID 27703239, 2016). "Other top GSTO1 inhibitors too showed cytotoxicity in a panel of cancer cell lines." (PMID 27703239, 2016). "Diplotype analysis showed that among subjects exposed to high levels of arsenic, the AGG/AGG variant of GSTO1 Ala140Asp, GSTO2 5'UTR (-183)A/G, and GSTO2 Asn142Asp was associated with an increased cancer risk (HRs, 4.91, 95% CI, 1.02-23.74) when compared to the all-wildtype reference, respectively." (PMID 21798077, 2011). "Therefore, GstO1 has been an attractive target for cancer treatment." (PMID 38791319, 2024). "The capacity of GSTO1-1 to specifically deglutathionylate proteins appears to be its primary physiological function and suggests a mechanism by which GSTO1-1 could potentially regulate cellular metabolism and signaling pathways that influence the growth and survival of cancer cells." (PMID 30487385, 2018). "Glutathione S‐transferase omega‐1 (GSTO1), an omega‐class GST (Glutathione S‐transferase), is crucial in regulating the S‐sulfation status of intracellular components involved in cancer cell viability and inflammatory processes." (PMID 38730525, 2024). "In contrast, other glutathione-related enzymes, such as GSTO1 (Glutathione S-Transferase Omega 1) and GSTP1 (Glutathione S-Transferase Pi 1), exhibited distinct expression patterns across different cancers, pointing to complex regulatory mechanisms at play." (PMID 39594421, 2024).
cancer (continued). "Inhibition of ryanodine receptor (RyR1) and glutathione S-transferase omega 1 (GSTO1) expression cleared off chemotherapy derivational BCSC enrichment and postponed cancer recurrence." (PMID 36632469, 2023). "Recent studies have also suggested that GSTO1 may be involved in the JAK/STAT3 signaling pathway, further highlighting its potential as a target for cancer therapy." (PMID 37047688, 2023). "KRAS mutant cancer cell lines (HCT116 and Panc-1) were more sensitive to GSTO1 inhibition." (PMID 27703239, 2016). "While GSTO1-1 has been shown to reduce methylated arsenic intermediates, in vitro studies have suggested that GSTP1 expression may promote arsenic methylation in cancer cells." (PMID 17284320, 2007). "Interestingly, ECA has been shown to possess inhibitory activity against GSTO1 in cancer, albeit not as potent as the classical inhibitor S2E." (PMID 37047688, 2023). "Studies have found that double gene knockout of GSTO1 and TNFαIP3/A20 using the CRISPR/Cas9 system is more sensitive to chemotherapy drugs than single gene knockout, and the apoptosis of cancer cells increases, which reveals that GSTO1 can enhance the drug resistance of cancer cells." (PMID 37020597, 2023). "Notably, GSTO1-1 has been identified as one of the proteins overexpressed in cisplatin-resistant ovarian cancer cell lines, although direct evidence of its role in cancer cell drug resistance is lacking." (PMID 37047688, 2023). "Although siRNA studies show that GSTO1 is important for HCT116 cancer cell viability, knockdown of GSTO1 did not appear to affect C1-27 cytotoxicity, suggesting that other targets of C1-27 also may contribute to its cytotoxicity and have a compensatory effect." (PMID 27703239, 2016). "Given the importance of ROS generation to the mechanism of mitoKv1.3 inhibitor mediated cell death, it is not surprising to see that cancer cells resistant to PCARBTP upregulated the antioxidant system (GSR, GSTO1, GSTA2, ALDH3A1)." (PMID 35681598, 2022). "We observed that KRAS mutant cancer cell lines (HCT116 and H460) and MDA-MB-435, with a high GSTO1 expression, were sensitive to GSTO1 knockdown, but not MCF7 cells." (PMID 27703239, 2016).
tumor (19 papers, 2013 to 2025). "The 6-protein diagnostic panel consisted of FLNA, PRDX6 and ARHGDIB, associated with tumor growth, cell invasion and metastasis, GSTO1, having an antioxidant defense role (together with PRDX6), TUBA4A, found enriched in serum exosomes from NSCLC patients, and the tumor suppressor CDH13." (PMID 32575471, 2020). "An uncritical evaluation of the data from the literature may show that some studies find an increased risk of a certain type of neoplasia in the presence of GSTO1*A140D or GSTO2*N142D polymorphisms, while just as many studies do not find significant correlations." (PMID 40724836, 2025). "On the other hand, an association between the GSTO1*A140 wild genotype with a susceptibility for nodal metastasis and an advanced tumor stage was found, leading to the suggestion that the GSTO1*A140D variant may have a protective role against HNSCC aggressiveness." (PMID 40724836, 2025). "The function of GSTO1 in chemoresistance was originally recognized via proteomic analysis by comparison between cisplatin‐resistant and parental tumor cells." (PMID 38750006, 2024). "This study found that TNF‐α was responsible for activating GSTO1 expression in macrophage–tumor coculture condition media." (PMID 38750006, 2024). "The tumor masses were significantly reduced in the GSTO1‐KO group subjected to cisplatin treatment, whereas cisplatin had no obvious effect on the GSTO1‐OE group compared to the control." (PMID 38750006, 2024). "The statistical analyses of tumor volumes showed that GSTO1‐KO significantly sensitized tumor cells to cisplatin treatment compared to parental cells, whereas GSTO1‐OE dramatically abolished the efficacy of cisplatin in tumor control." (PMID 38750006, 2024). "Interaction of GSTO1 with downstream effectors of investigated pathways was shown in ccRCC tumor tissue." (PMID 31861116, 2019). "We evaluated correlation between GSTO1 expression and IL-1β/pro-IL-1β ratio in tumor ccRCC tissue samples and observed weak positive correlation (r = 0.260, p = 0.350)." (PMID 31861116, 2019). "Densitometry analysis following Western blot showed 1.5-fold higher expression of GSTO1 in tumor ccRCC compared to non-tumor tissue (p = 0.002)." (PMID 31861116, 2019). "We evaluated the expression of GSTO1 in various tumour types using publicly available gene expression data sets from the Oncomine database." (PMID 27703239, 2016). "Inhibition of IL-1β secretion by GSTO1 inhibitors also has exciting implications on tumour progression and tumour-immune cell crosstalk in the microenvironment." (PMID 27703239, 2016). "BODIPY-C1-27A labelling of GSTO1 was decreased in C1-27-treated tumours compared with the control group." (PMID 27703239, 2016). "Since, the majority of TCC patients with GSTO1 or GSTO2 polymorphisms died, it would imply the anti-tumor role of AA in TCC progression." (PMID 24040330, 2013). "If such kind of regulation of GSTO2 expression also exists in TCC cells, GSTO1 or GSTO2 polymorphisms would presumably result in deficient DHAR activity, and lower ascorbic acid level (AA) in tumor." (PMID 24040330, 2013). "In addition, recent studies implicate critical roles for GSTO1 in pro‐inflammatory and oxidative stress in diverse types of cells, including immune cells and tumor cells." (PMID 38750006, 2024). "In addition, the ICP‐MS analysis showed that the Pt content was significantly higher in the GSTO1‐KO tumor tissue than in the tumor tissue of the control." (PMID 38750006, 2024). "Interestingly, in tumor specimens of GSTO1*CC wild-type genotype carriers, higher GSTO1 expression was found in comparison with those carrying at least one variant allele." (PMID 31861116, 2019). "Furthermore, our study showed a weak correlation between IL-1β/pro- IL-1β ratio, as a degree of IL-1β activation, and the level of GSTO1 expression in ccRCC tumor tissue." (PMID 31861116, 2019).
tumor (continued). "Furthermore, expression of SLC7A11, a GSTO1 and C1-27 target gene, was increased in C1-27-treated tumours indicating target engagement." (PMID 27703239, 2016). "We further examined in vivo binding of C1-27 to GSTO1 using the PDX tumour tissue homogenates." (PMID 27703239, 2016). "Furthermore, tumor cell lines overexpressing GSTO1 have been reported to resist to cis-platinum treatment through activation of the Akt and ERK 1/2 survival pathways." (PMID 26046795, 2015). "RyR1 expression is elevated in chemotherapy-resistant BCSCs, where it promotes calcium release via the glutathione S-transferase omega 1 (GSTO1) pathway; blocking this channel reduces CSC markers like Nanog and tumour volume in mouse models." (PMID 40806720, 2025). "Given that GSTO1 is a crucial cellular antioxidant enzyme, the inhibition of its activity by ECA represents a promising avenue for tumor-targeted therapy." (PMID 37047688, 2023). "In these pathways, some genes including an oxidative stress response gene (GSTO1), a metastasis suppressor gene (NME6), and a gene involved in tumor cell survival (UCKL1), were upregulated." (PMID 37744913, 2023). "However, genes involved in antioxidant defense (GSTO1), apoptosis process (DUSP8), and tumor suppressor (KIAA1324, FBXO47, NME6) were upregulated in mycotoxins-exposed animals, suggesting activation of the antioxidant defense in response to mycotoxicity." (PMID 37744913, 2023). "Moreover, chemotherapy induces the expression of GSTO1, which is dependent of HIF-1 and HIF-2, and knockdown of GSTO1 expression abrogates carboplatin-induced BCSC enrichment, decreasing tumor initiation and metastatic ability, and delaying tumor relapse." (PMID 33184339, 2020). "It has been showed that chemotherapy induces the expression of glutathione S-transferase omega 1 (GSTO1) and further knockdown of GSTO1 expression, abrogates carboplatin induced BCSC enrichment, decreases tumor initiation, metastatic ability, and delays tumor recurrence after chemotherapy." (PMID 33184339, 2020). "In addition, GSTA1, GSTM1, and GSTZ1 are reported to be downregulated in tumor tissue and can correlate with a poor prognosis, while GSTT1, GSTO1, and GSTK1 are mostly reported to be upregulated in tumor tissue compared to the normal surrounding tissue." (PMID 33228209, 2020). "Furthermore, we evaluated GSTO1-1 and GSTO2-2 expression in ccRCC and adjacent non-tumor tissue, as well as phosphorylation status of two important survival pathways, PI3K/Akt/mTOR and Raf/MEK/ERK." (PMID 31861116, 2019). "In ccRCC tumor tissue, in comparison with the corresponding non-tumor tissue, increased expression of both GSTO1 and GSTO2 was determined." (PMID 31861116, 2019). "Up-regulated GSTO1-1 and GSTO2-2 in tumor tissue might contribute to aberrant ccRCC redox homeostasis." (PMID 31861116, 2019). "Moreover, interaction of GSTO1 with activated downstream effectors of PI3K/Akt/mTOR and Raf/MEK/ERK pathway was shown in ccRCC tumor tissue." (PMID 31861116, 2019). "Increased expression of GSTO1-1 and GSTO2-2 was demonstrated in tumor compared to corresponding non-tumor tissue (p = 0.002, p = 0.007, respectively), while GSTO1 expression was correlated with interleukin-1β (IL-1β)/pro-interleukin-1β (pro-IL-1β) ratio (r = 0.260, p = 0.350)." (PMID 31861116, 2019). "Furthermore, up-regulated GSTO1-1 and GSTO2-2 enzymes in ccRCC tumor tissue might contribute to aberrant redox homeostasis." (PMID 31861116, 2019). "Our results showed significantly higher protein expression of GSTO1 and GSTO2 in tumor ccRCC tissue compared to non-tumor tissue." (PMID 31861116, 2019).
infection (7 papers, 2013 to 2025). The state of being infected such as from the introduction of a foreign agent such as serum, vaccine, antigenic substance or organism. "In contrast, genes such as metalloprotease-like protein, cytochrome P450 3A9, and glutathione S-transferase omega-1 are significantly upregulated at later time points (96 and 144 h), suggesting an increased reliance on proteolysis, detoxification, and secondary metabolism as the infection advances." (PMID 40611938, 2025). "In this study, after the injection of NAC oxidative stress levels were significantly reduced in the pathogen infection group and the mRNA levels of SOD, CAT, GSTCD, and GSTO1 increased significantly." (PMID 33574492, 2021). "The gsto-1 locus is transcriptionally regulated by the GATA transcription factor ELT-2, leading us to consider a role for ELT-2 in controlling the expression of a set of genes required for resolution of an infection." (PMID 25340560, 2014).
neurodegenerative disease (5 papers, 2014 to 2024). A disorder of the central nervous system characterized by gradual and progressive loss of neural tissue and neurologic function. "The glutathione S-transferase omega 1 (GSTO1) and 2 (GstO2, the Drosophila homolog of human GSTO1) were found to be involved in the oxidative damage underlying the pathogenesis of neurodegenerative diseases." (PMID 38339026, 2024). "Moreover, GSTO1 regulates the activation of interleukin-1β and stops the inflammation process in aging-associated neurodegenerative disease." (PMID 35767571, 2022). "GSTO1 has diverse functions, including mitigation of oxidative stress, and may underlie the pathophysiology of several neurodegenerative diseases." (PMID 25248508, 2014). "Another protein, GSTO1, modulates conjugation of GSH, the activation of interleukin-1β, and inflammation in aging-associated neurodegenerative disease." (PMID 35767571, 2022).
bacterial infection (1 paper, 2022). "Thus, lower levels of GSTO1 in the circulation of Ai-DKO mice suggests that their capacity to cope with diet-induced inflammation or bacterial infection might be altered, although this was not examined." (PMID 35964946, 2022).